ITGA2 (integrin subunit alpha 2)
Diseases named in the same sentence as ITGA2 in open-access papers (continued):
Sharing a sentence is not in itself a finding about the gene and the disease.
cancer (continued). "Furthermore, immune checkpoint treatment has become a new method to treat cancer and ITGA2 can bring new insights into targeted immunotherapy and, for patient with LGG, may represent a potential molecular marker for targeted therapy." (PMID 35936750, 2022). "The aberrant glycosylation of integrins have been implicated in multiple cancers, however, natural variants that cause loss or gain of function due to individual glycosylation sites have not been reported for ITGA2 so far." (PMID 34646995, 2021). "Our results indicate that knocking down ITGA2 could inhibit cancer aggression in vitro." (PMID 31818309, 2019). "However, the specific biological mechanism of how the expression of ITGA2 correlates with the progression of cancer and the blockade of ITGA2 inhibits the migration of cancer cells has remained unknown for a long time." (PMID 31818309, 2019). "However, the ITGA2 protein level was significantly recovered in lymph node metastases compared to primary cancer, suggesting that ITGA2 up-regulation in detached cancer cells in blood vessels or the lymphatic system was helpful for location and interaction with ECM in lymph node and distant tissues." (PMID 26258411, 2015). "The controversial effects of ITGA2 on cancer metastasis might be explained by our observations." (PMID 26258411, 2015). "While the serum integrin glycovariant levels were low overall, serum ITGA2–UEA offered significant resolution in both radiotherapy response prediction and cancer recurrence prognostication." (PMID 40287842, 2025). "More importantly, several cell adhesion proteins, such as BSG, ITGA2, CD9, SLC3A2 or CD151, were significantly enriched in TuNEPs and shared across cancer types." (PMID 40751052, 2025). "Our transcriptomic analyses of CM-treated HOSEs uncovered gene-expression profiles defining responses to cancer-like TME, highlighted by STAT1, ISG15, and OAS1 in HOSE1C and ITGA2, GREM1, and CDH13 in HOSE2C." (PMID 39634630, 2024). "The N-glycosylation of integrin alpha 2 (ITGA2) affects cell–ECM adhesion, which promotes cancer metastasis by selectively adhering to ECM proteins." (PMID 38248854, 2024). "Considering the fact that ITGB4, ITGA2, and ITGA6 were frequently up-regulated in cancer vs. normal tissues, our results suggest potential protumorigenic roles for them." (PMID 39436262, 2024). "Overexpression of ITGA2 can activate the STAT3 signal pathway and upregulate the expression of PD-L1, thus promoting the invasion of malignant tumors, which are closely related to immunity." (PMID 37907515, 2023). "Multiple integrin genes are known to be regulated in cancer by DNA methylation at their promoter regions including ITGA1, ITGA2, ITGA4, ITGA7, and ITGA9, and some (e.g., ITGA2) are known to be regulated by histone modifications including H3K27me3." (PMID 36512308, 2023). "In CRC, LINC00355 promotes ITGA2 expression by recruiting GTF2B, a critical transcription factor involved in regulating various cancers, thereby promoting cancer progression." (PMID 38125763, 2023). "The expression rates of ITGA2, CD4, and CD8 were found to be significantly higher in cancer tissues compared to adjacent tissues." (PMID 37881431, 2023). "LINC00355 induces chemotherapy resistance in cancer cells by regulating five downstream genes, namely HMGA2, ABCB1, ITGA2, WNT10B, and CCNE1 genes." (PMID 38125763, 2023). "The overexpression of ITGA2 has been found to enhance cell proliferation and promote cancer cell invasion through the activation of the PD-L1 and EMT in various cancers." (PMID 37881431, 2023). "The mRNA expression level of ITGA2 has been found to be significantly higher in gastric cancer tissues compared to normal tissues, is closely associated with other cancers such as pancreatic cancer and CRC, and therefore could be a potential therapeutic target for these cancers." (PMID 36338118, 2022).
cancer (continued). "Many cancer-cell invasion and migration-promoting genes such as SERPINE1, PLSCR1, ITGA2, MMP14, etc. are significantly down-regulated in the IGROV1 cells." (PMID 34949722, 2022). "In cancer cells, direct high-affinity interaction between IGFBP5 and α2β1 integrin (aka ITGA2) has been reported." (PMID 34830489, 2021). "This is in contrast to studies in which ITGA2 and ITGB1 have been found to suppress metastasis in models of mouse and human cancer." (PMID 33276802, 2020). "In Caco-2 cells, LAD1 KD slightly reduced the mRNA expression of integrins such as ITGA2, ITGB1, and ITGA6, which are involved in cancer cell motility." (PMID 33267790, 2020). "In the current study, the divergent cancer subtypes of ILC and IDC, which differ in regard to their EMT status, were studied as PDXs in order to examine the relationship between EMT, ITGA2/B1 and ILK in cancer progression, through serial passages in mice." (PMID 33276802, 2020). "In this study, we have systematically evaluated a panel of 70 cancer-related antigens in GBM cells and have identified ITGA2 as a promising new target for GBM." (PMID 30996239, 2019). "Overall, our findings suggest that ITGA2 enhances STAT3 phosphorylation by serving as the origin of the transcription and translation of PD-L1 in cancer cells." (PMID 31818309, 2019). "To determine the relationship between ITGA2 and the STAT3 signaling pathway, we, first of all, examined the mRNA expression level of STAT3 in cancer cells infected with sh-Control or sh-ITGA2." (PMID 31818309, 2019). "We further revealed that ITGA2 interacted with STAT3 and up-regulated PD-L1 expression by increasing the phosphorylation of STAT3 in cancer cells." (PMID 31818309, 2019). "The DCGs, including GART, TGFB1, ITGA2, SLC16A5, SOX9, and MMP7, were investigated across 12 cancer types." (PMID 29843204, 2019). "According to the information from the Cancer Cell Line Encyclopedia (CCLE) database, the AGS cell line with ITGA2 high expression and the SUN-1 cell line with low expression were chosen for the further investigation." (PMID 29743821, 2018). "FZD8, plasminogen activator, urokinase receptor, ITGA2, WNT2B, TIMP3, WNT5B, FGF5, heparanase, HBEGF and WNT3A were up-regulated in the proteoglycan pathways in cancer, whereas WNT10A, PIK3R3, IGF2 were down-regulated." (PMID 30482199, 2018). "In conclusion, our results suggested the important roles of ITGA2, FN1, ICAM1, TIMP1 and CDH2 in the progression of PTC via various cancer-related pathways." (PMID 30414611, 2018). "Camptothecin amplified the effects seen in cancer (CHECK2, BCL-2 and IL8), but opposed them for CYP51A1, ITGA2, DHCR7 or HMGCS1." (PMID 28962550, 2017). "It has been previously shown that ITGA2 is enriched in ECM-receptor interactions and pathways in cancer." (PMID 28947976, 2017). "Cancer Pathway cDNA microarray analysis revealed that DACT1α down-regulated cell adhesion receptors from the integrin family including ITGA1, ITGA2, ITGA3 and ITGB3." (PMID 27833078, 2016). "Therefore, we speculate that ITGA2 may play a dual role in cancer metastasis." (PMID 26258411, 2015). "Of note, ITGA2 is an appealing therapeutic target not only in PDAC, but also in other cancer types." (PMID 36765586, 2023). "Additionally, the overexpression of ITGA2 activates the STAT3 signaling pathway, leading to the up-regulation of PD-L1 expression and promoting malignant tumor invasion." (PMID 37881431, 2023). "For cancer cells, cholesterol inhibition during 3D culture increased levels of ECM modification enzyme Mmp3, the integrin Itga2, and inflammation response factors Ptges and Areg; these trends in all genes were consistently reversed when exogenous cholesterol was added." (PMID 37626861, 2023). "Also, ITGA2, ITGA3 and ITGA6 are integrin coding genes that participate in cell adhesion, proliferation, and differentiation and are known to have anti-cancer properties in LC." (PMID 35600397, 2022).
cancer (continued). "Among these proteins, the overexpression of MMP14, ITGA2, THBS2, COL1A1, COL3A1, COL11A1 and COL6A3 has been experimentally confirmed in PDAC, while that of COL12A1 and COL5A2 has been shown in other types of cancer." (PMID 34094925, 2021). "The overexpressed integrin α (ITGA) subfamily genes ITGA2 and ITGA3 are predicted to be involved in cancer-related pathways such as PI3K-Akt signaling pathway and FA interacting with ECM genes such as laminin (LAMB3, LAMA3, and LAMC2) and collagen (COL10A1, COL12A1)." (PMID 34262595, 2021). "Although integrin alpha 2 subunit (ITGA2) mediates cancer progression and metastasis, its transfer by exosomes has not been investigated in prostate cancer (PCa)." (PMID 32824235, 2020). "The ITGA2-dependent phosphorylation of FAK and ERK1/2 triggers focal adhesion and MAPK signaling, leading to increased anoikis resistance and mesothelial invasion of cancer cells." (PMID 33026975, 2020). "Overexpression of both ITGA2 and ITGB1 was detected in these cancer lesions." (PMID 32899691, 2020). "Similarly, the overexpression of ITGA2 increased the phosphorylation level of STAT3 and protein level of PD-L1 in cancer cells, and these effects were diminished by STAT3 inhibitor treatment." (PMID 31818309, 2019). "Fifteen members of cancer pathways, including FOS, TGFα, FZD8, MMP1, laminin subunit gamma 2, PTGS2, laminin subunit beta 3, ITGA2, laminin subunit alpha 3, VEGFC, WNT2B, heat shock protein 90 beta family member 1, WNT5B, FGF5 and WNT3A, were up-regulated in the MC group." (PMID 30482199, 2018). "Based on these results, the expression of ITGA2, BMP4 and PLCB1 may contribute to cancer development." (PMID 28947976, 2017). "Some of these treatments could oppose the deregulations occurring in cancer samples, including those of the CHECK2, CYP51A1, HMGCS1, ITGA2, NME1 or VEGFA genes." (PMID 28962550, 2017). "ITGA2 knockdown stimulated cancer cell migration but did not affect cancer invasion, similar to our previous report that the influences of miR-373 on cancer migration." (PMID 26258411, 2015). "Notably, none of these pairs have been directly associated with TGFβ signaling or EMT, although many of the identified ligands (e.g., LAMC2) or receptors (e.g., CD151, COL17A1, ITGA2, ITGA3, ITGA6, ITGB1, and ITGB4) occur frequently in the context of EMT and/or cancer." (PMID 36755019, 2023). "Enhanced expression of ITGAV (αv subunit), ITGA1 (α1 subunit) and ITGA2 (α2 subunit) in OVCAR5 CBPR cells is indicative of ECM changes consistent with enhanced production of fibronectin and collagen observed in several malignancies and in most EMT-induced cancer models." (PMID 36463238, 2022). "Moreover, glycoproteomic experiments have been performed in cancer cells only and our ITGA2-glycosylation data are therefore not necessarily reflective of ITGA2 glycosylation from “normal” cells." (PMID 34646995, 2021). "We also demonstrated that ITGA2 interacted with STAT3 and up-regulated the phosphorylation of STAT3; this interaction might involve the mechanism of ITGA2 inducing PD-L1 expression in cancer cells." (PMID 31818309, 2019). "Co-transfection of ITGA2 blocked miR-373-induced cancer cell migration, but ITGA2 3’UTR did not." (PMID 26258411, 2015). "Therefore, ITGA2 and FN1 may play key roles in PTC progression via these cancer-related pathways." (PMID 30414611, 2018). "The co-expression of ITGA2, not ITGA2-3’UTR, could abrogate miR-373-induced cancer cell migration because that the expression of ITGA2-3’UTR was inhibited by co-transfected miR-373." (PMID 26258411, 2015). "The co-expression of ITGA2, not ITGA2-3’UTR, could block miR-373-induced cancer migration." (PMID 26258411, 2015).
infection (28 papers, 2009 to 2025). The state of being infected such as from the introduction of a foreign agent such as serum, vaccine, antigenic substance or organism. "However, vaccinated mice exhibit an undulatory reciprocal increase of Itga1 and Itga2 expression during infections." (PMID 33202767, 2020). "The duplicated copies of integrin alpha 2 (ITGA2) on ssa01 and ssa13 as well as copies of thrombospondin-1 (THBS1) on the homeologous segments of ssa01 and ssa09 showed significant up-regulation during the second infection." (PMID 30873203, 2019).
gastrointestinal tumors (2 papers, 2024 to 2025). "Here, our primary objective is to review the biological function and molecular mechanism of ITGA2 in gastrointestinal tumors, alongside conducting a comprehensive analysis of the existing understanding of ITGA2 in the regulation of the TME." (PMID 39568561, 2024). "Therefore, we mainly focus on the research of ITGA2 in gastrointestinal tumors and their microenvironment in this review, aiming to provide a potential new marker for guiding the treatment and prognosis of many gastrointestinal tumors." (PMID 39568561, 2024).
immune system diseases (1 paper, 2015). "Specifically, eight genes (IRF5, UBA7, TMTC1, GSTM3, FBN2, OAS1, PODXL, ITGA2) were previously associated with immune system diseases in at least one study." (PMID 25874939, 2015).
renal disease (1 paper, 2010). "Future studies should concentrate on the role of ITGA2 in renal disease and on the possible balancing role of both ITGA2 and DDR1." (PMID 20860797, 2010).
reproductive diseases (1 paper, 2024). "Evidence proposed that the dysregulation of STC1, TIMP3, ITGA2, and INHBA is associated with the development of severe reproductive diseases." (PMID 38730500, 2024).
ITGA2 also shares sentences with these, for which no sentence is quoted: Stroke (7 papers); non-small cell lung carcinoma (5); myocardial infarction (4); Thrombocytopenia (4); viral infection (4); cardiovascular disease (3); colitis (3); endometrial cancer (3); Glanzmann thrombasthenia (3); heart failure (3); leiomyoma (3); pancreatic ductal adenocarcinoma (3); psoriasis (3); abortion (2); chondrosarcoma (2); chronic kidney disease (2); diabetes type I (2); fibrosis (2); gastric tumor (2); hypertension (2); keloid (2); Kidney stone (2); lung squamous cell carcinoma (2); oral cancer (2); rhabdomyosarcoma (2); serous ovarian cancer (2); acute GVHD (1); acute myocardial infarction (1); acute promyelocytic leukemia (1); adenocarcinoma (1).
A further 76 diseases each share a sentence with ITGA2 in 1 paper.